NAT10 (N-acetyltransferase 10)
Diseases named in the same sentence as NAT10 in open-access papers (continued):
Sharing a sentence is not in itself a finding about the gene and the disease.
osteosarcoma (7 papers, 2024 to 2025). A usually aggressive malignant bone-forming mesenchymal neoplasm, predominantly affecting adolescents and young adults. "To determine whether NAT10 regulated ac4C acetylation plays a role in osteosarcoma cells, we conducted loss-of-function studies." (PMID 38233839, 2024). "This study reveals the critical role of the NAT10/ac4C–YTHDC1/m6A–LDHA/PFKM signaling axis in osteosarcoma." (PMID 39764566, 2025). "Knocking down NAT10 significantly increases m6A levels and markedly inhibits the growth, migration, and invasion of osteosarcoma cells." (PMID 39764566, 2025). "For instance, in human osteosarcoma tissues, NAT10 knockdown significantly upregulates m6A modification levels while inhibiting the growth, migration, and invasion of osteosarcoma cells." (PMID 39764566, 2025). "A recent study found that the key ac4C acetylation enzyme NAT10 is highly expressed in human osteosarcoma tissues." (PMID 39764566, 2025). "In osteosarcoma, NAT10 enhances mRNA stability of activating transcription factor 4 (ATF4) through ac4C modification." (PMID 40588654, 2025). "Our article shows that YTHDC1 transcript was a critical target gene for ac4C acetylation, while indeed affects glycolysis in osteosarcoma cells by examining differences in glucose, lactate, and pyruvate content in cells or media after NAT10 knockdown." (PMID 38233839, 2024). "Available evidence demonstrates the increased ac4C modification levels and expression of the writer protein NAT10 in osteosarcoma (OS)." (PMID 39640362, 2024). "RNA dot blot revealed that ac4C content was significantly decreased in osteosarcoma cells after transfected with NAT10 siRNA." (PMID 38233839, 2024). "Altogether, we found ac4C driven RNA m6A modification can positively regulate the glycolysis of cancer cells and reveals a previously unrecognized signaling axis of NAT10/ac4C-YTHDC1/m6A-LDHA/PFKM in osteosarcoma." (PMID 38233839, 2024). "Given the known crucial role of NAT10 in various types of tumors, there has been an intense focus on characterizing the effects of this enzyme on the development and progression of osteosarcoma." (PMID 38233839, 2024). "In this study, we demonstrate for the first time that ac4c driven RNA m6A modification can positively regulate the glycolysis of cancer cells and reveals a previously unrecognized signaling axis of NAT10/ac4C-YTHDC1/m6A-LDHA/PFKM in osteosarcoma." (PMID 38233839, 2024). "Significantly higher NAT10 protein expression was detected in osteosarcoma cores compared with normal bone tissues." (PMID 38233839, 2024). "Here, we have identified that a key enzyme in N4-acetylcytidine (ac4C) acetylation NAT10 is highly expressed in human osteosarcoma tissues, and its knockdown enhanced m6A contents and significantly suppressed osteosarcoma cell growth, migration and invasion." (PMID 38233839, 2024). "We then applied immunohistochemistry (IHC) assays to measure NAT10 protein expression in an osteosarcoma tissue microarray (TMA) containing 71 tissue cores as compared with normal bone tissues." (PMID 38233839, 2024). "Next, we investigated the potential mechanism of NAT10 in regulating glycolysis in osteosarcoma cells." (PMID 38233839, 2024). "Together, these findings demonstrate a mechanism of ac4C driven RNA m6A modification and reveals a previously unrecognized signaling axis of NAT10-YTHDC1-LDHA/PFKM in osteosarcoma, shedding new light on the epigenetic regulation in human cancer." (PMID 38233839, 2024). "Like other diseases, our study reveals that NAT10 is highly expressed in osteosarcoma patients, and its abnormal levels predict disease progression and lower overall survival." (PMID 38233839, 2024). "Therefore, NAT10-dependent ac4C acetylation regulates the m6A methylation levels of osteosarcoma cells." (PMID 38233839, 2024). "Therefore, we propose targeting NAT10 as a promising therapeutic strategy for osteosarcoma treatment." (PMID 38233839, 2024).
osteosarcoma (continued). "Therefore, our findings suggest that NAT10 serves as an effective and novel therapeutic target for osteosarcoma through YTHDC1-mediated m6A modification, which can impact the translation efficiency of LDHA and PFKM." (PMID 38233839, 2024). "Importantly, NAT10 is sufficient and necessary for the tumorigenic properties of osteosarcoma." (PMID 38233839, 2024). "Despite these challenges, targeting NAT10 and YTHDC1 remains a promising therapeutic strategy for various diseases, including osteosarcoma." (PMID 38233839, 2024). "Molecular therapy targeting NAT10 and YTHDC1 has shown potential for the treatment of various diseases, including osteosarcoma." (PMID 38233839, 2024). "The results showed that depleting NAT10 decreased the colony-formation capacity of U2OS and 143B osteosarcoma cells." (PMID 38233839, 2024). "NAT10 was also reported to regulate lactate production and pyruvate content through YTHDC1, which is ac4C modified by NAT10 and mediated m6 A methylation of PFKM and LDHA RNAs in osteosarcoma." (PMID 40588654, 2025). "Furthermore, lentiviral depleting NAT10 remarkably inhibited the colony-formation capacity in both U2OS and 143B osteosarcoma cells in colony-formation assays, lentiviral overexpression of YTHDC1 significantly abolished this effect." (PMID 38233839, 2024). "Additionally, our study is the first to reveal that NAT10-mediated YTHDC1 mRNA decay is partially due to the reduced stability of its mRNA transcript, leading to the inhibition of protein translation and suppressing osteosarcoma cell growth." (PMID 38233839, 2024).
systemic lupus erythematosus (7 papers, 2020 to 2025). An autoimmune multi-organ disease typically associated with vasculopathy and autoantibody production. "Beyond oncology, NAT10 dysregulation is associated with autoimmune diseases like rheumatoid arthritis and systemic lupus erythematosus, where it modulates immune responses through RNA acetylation." (PMID 40588654, 2025). "Moreover, several studies also show that level of NAT10 are associated with inflammatory responses and systemic lupus erythematosus (SLE)." (PMID 38167491, 2024). "A recent study observed a significant reduction in the RNA expression of NAT10 in CD4+ T cells from systemic lupus erythematosus (SLE) patients compared to healthy controls, along with a decrease in ac4C modification." (PMID 40038243, 2025). "Meanwhile, significantly lower mRNA acetyltransferase NAT10 expression was detected in lupus CD4+ T cells by RT-qPCR." (PMID 32984334, 2020). "In systemic lupus erythematosus, abnormal NAT10 expression shows a significant correlation with global ac4C levels, suggesting its involvement in the pathogenesis of autoimmune disorders through the regulation of ac4C modification in downstream target gene transcripts." (PMID 41446042, 2025). "For instance, systemic lupus erythematosus (SLE) patients display reduced NAT10 levels in their CD4+ T cell populations when benchmarked against healthy subjects." (PMID 41472140, 2025). "Studies have shown that NAT10 and global ac4C levels are downregulated in CD4+ T cells from patients with systemic lupus erythematosus (SLE), with abundant ac4C peaks in mRNA CDSs and 3′ UTR regions, indicating dysregulation of ac4C modifications in SLE." (PMID 39764566, 2025).
esophageal squamous cell carcinoma (6 papers, 2025). Esophageal squamous cell carcinoma (ESCC) is a type of esophageal carcinoma (EC) that can affect any part of the esophagus, but is usually located in the upper or middle third. "In esophageal squamous cell carcinoma, NAT10 stabilizes the expression of fatty acid synthase (FASN) by mediating ac4C modification, thereby promoting the M2 polarization of macrophages." (PMID 40767620, 2025). "In esophageal squamous cell carcinoma (ESCC) cells, overexpression of NAT10 triggers epithelial‒mesenchymal transition (EMT), thereby enhancing tumor invasion and metastasis through fibronectin-mediated filamentous foot formation." (PMID 41316475, 2025). "NAT10 also mediates the ac4C modification of lncRNA CTC-490G23.2, which leads to the stabilization and overexpression of CTC-490G23.2 in primary esophageal squamous cell carcinoma and its further upregulation in metastatic tissues." (PMID 40588654, 2025).
ovarian carcinoma (6 papers, 2021 to 2025). A malignant neoplasm originating from the surface ovarian epithelium. "NAT10 was involved in tubulin processing, associated with cell growth in epithelial ovarian cancer." (PMID 36545327, 2022). "NAT10 also promotes ovarian cancer cell migration and invasion by mediating the ac4C modification of CAPRIN1 mRNA." (PMID 41316475, 2025). "In addition to Remodelin, fludarabine has also been found to be an inhibitor of NAT10 in acute myeloid leukemia and ovarian cancer." (PMID 41316475, 2025). "In ovarian cancer, NAT10 promotes tumorigenesis by mediating the ac4C modification of ACOT7 mRNA." (PMID 41316475, 2025). "Also, in different stages of these six types of cancer, the total protein of NAT10 showed higher expression in the primary tumor except ovarian cancer." (PMID 34094911, 2021).
viral infection (6 papers, 2022 to 2025). "Emerging studies have demonstrated that viral infection is linked to aberrant RNA N4-acetylcytidine (ac4C) modification, which is dependent on N-acetyltransferase 10 (NAT10)." (PMID 39925738, 2025). "KEGG pathway analysis revealed enriched pathways implicated in virus infection, while Hippo signaling pathway was the most enriched one in NAT10 knockdown cells." (PMID 37816771, 2023). "In order to ascertain the impact of NAT10-regulated IgA on viral infections, we conducted a study assessing the immune response to viral challenge in NAT10cKO mice." (PMID 40615576, 2025). "This review summarizes the structural and functional roles of NAT10-mediated acetylation in physiological contexts, including cell division, differentiation, inflammation, aging, and viral infection, as well as its emerging roles in cancer." (PMID 40881352, 2025). "The SINV RNA in the NAT10-KD cells was significantly reduced at 12 and 24 hpi, suggesting that NAT10 plays a role in the later stages of viral infection." (PMID 38169284, 2024). "Thus, we summarize the specific roles of NAT10-mediated acetylation modifications in inflammatory diseases, aging-related diseases, and viral infections." (PMID 40881352, 2025). "First, As NAT10 loss enhanced degradation of the LY6E mRNA transcripts after viral infection, other genes may also contribute to the NAT10-mediated ac4C modifications that impact SINV replication." (PMID 38169284, 2024). "In 2020, the first report on the role of ac4C in viral infection revealed that multiple cytidines on HIV-1 RNAs are acetylated to ac4C by cellular NAT10, while silent mutagenesis of these ac4C sites led to inhibited HIV-1 replication by reducing viral RNA stability." (PMID 37816771, 2023). "EV71 acetylation was catalyzed by host NAT10, which in turn promoted viral infection." (PMID 35971620, 2022). "Western blotting also revealed that more NAT10 was distributed in the cytoplasmic fraction after virus infection, indicating that EV71 altered the subcellular localization of NAT10." (PMID 35971620, 2022). "Among them, 97 genes were downregulated in NAT10-KD cells, while 30 were upregulated after SINV infection, indicating that most were downregulated after NAT10 depletion and that the NAT10 knockdown enhanced mRNA transcript reduction after viral infection." (PMID 38169284, 2024). "A stronger signal for NAT10 was detected during virus infection in immunofluorescence experiments, implying that EV71 infection may enhance NAT10 expression." (PMID 35971620, 2022).
heart failure (5 papers, 2024 to 2025). Inability of the heart to pump blood at an adequate rate to meet tissue metabolic requirements. "Cardiac remodeling, a hallmark of heart failure, is mediated by NAT10-mediated ac4C acetylation modification." (PMID 40588654, 2025). "Emerging evidence indicates that genetic depletion of NAT10 triggers cardiomyocyte apoptosis, a critical determinant in the progression of heart failure pathophysiology." (PMID 40588654, 2025). "A study with a mouse model found that knockdown of Nat10 induces cardiomyocyte apoptosis and heart failure." (PMID 39728482, 2024). "NAT10 is involved in the process of heart failure especially by promoting cardiac remodeling." (PMID 40588654, 2025). "NAT10 may be a promising therapeutic target against cardiac remodeling and heart failure." (PMID 40588654, 2025).
laminopathies (5 papers, 2014 to 2021). "Human NAT10 has also been linked to laminopathies because it is the target of remodelin, a chemical compound used to treat premature aging syndromes; inactivation of NAT10 corrected nuclear defects via microtubule reorganization." (PMID 31491951, 2019). "Remodelin is a small-molecule compound explored as potent inhibitor of NAT10 and firstly reported that targeting NAT10 might be an alternative strategy for the treatment of laminopathies and aging." (PMID 34362389, 2021). "N-acetyltransferase 10 (NAT10) has been considered a target for the treatment of human diseases such as cancer and laminopathies; however, its functional role in the biology of melanocytes is questionable." (PMID 28880216, 2017). "NAT10 is the target of a small molecule compound called ‘remodelin’ to treat laminopathies and premature ageing syndromes, not yet tested in the context of HCC." (PMID 30662724, 2018).
nasopharyngeal carcinoma (5 papers, 2025). A carcinoma arising from the nasopharyngeal epithelium. "The stability of lncRNA SIMALR is enhanced by NAT10-mediated acetylation and its overexpression in nasopharyngeal carcinoma functions as the oncogenic role." (PMID 40588654, 2025). "In nasopharyngeal carcinoma, NAT10 expression is upregulated." (PMID 40588654, 2025). "NAT10 enhances the stability of SIMALR through ac4C modification, which in turn facilitates the proliferation and metastasis of nasopharyngeal carcinoma cells." (PMID 40767620, 2025). "NAT10 promotes solute carrier family 7 member 11 (SLC7 A11) expression through ac4C acetylation, which inhibits sorafenib-induced ferroptosis in nasopharyngeal carcinoma cells." (PMID 40588654, 2025). "In nasopharyngeal carcinoma (NPC), the same family of HMGB2, high mobility group box 1 (HMGB1), the direct target of dead box helicase 5 (DDX5), is upregulated by the NAT10-mediated ac4C modification of DDX5, which inhibits the T-cell immunity of CD4 + and CD8 + T cells and promotes NPC progression." (PMID 41316475, 2025). "Notably, NAT10 extends its regulatory reach beyond protein-coding RNAs—ac4C modification of lncRNA SIMALR enhances its stability, enabling activation of eEF1 A2-mediated ITGB4/ITGA6 translation in nasopharyngeal carcinoma." (PMID 40588654, 2025).
osteoporosis (5 papers, 2023 to 2025). A condition of reduced bone mass, with decreased cortical thickness and a decrease in the number and size of the trabeculae of cancellous bone (but normal chemical composition), resulting in increased fracture incidence. "In addition, low NAT10 expression levels were observed in ovariectomy (OVX) mice and patients with osteoporosis." (PMID 39817252, 2025). "Furthermore, NAT10 directly controls the expression of RUNX2 through ac4C modification, regulating osteoblast differentiation ability of BMSC in vitro; thus, it can be used as a new potential therapeutic target for osteoporosis." (PMID 38233839, 2024).
depression (4 papers, 2023 to 2025). "In a study conducted on mice, chronic mild stress (CMS) was used to trigger anxiety and depression-like behavior, and the results indicated an increase in NAT10 expression in the hippocampus following the administration of CMS." (PMID 37644009, 2023). "Recently, Guo and colleagues found that NAT10 elevation in hippocampal neurons was related to anxiety- and depression-like behavior." (PMID 37763159, 2023).
glioblastoma (4 papers, 2024 to 2026). The most malignant astrocytic tumor (WHO grade IV). "Functionally, NAT10 promotes glioblastoma cell proliferation and migration in vitro and accelerates tumor growth in vivo." (PMID 41507133, 2026). "In this study, we elucidated the role of NAT10 in enhancing glioblastoma (GBM) stemness by promoting JARID2 expression." (PMID 40288646, 2025). "However, the biological functions and regulatory mechanisms of NAT10-mediated ac4C modification in glioblastoma (GBM) remain largely unclear." (PMID 41507133, 2026).
glioma (4 papers, 2015 to 2025). A benign or malignant brain and spinal cord tumor that arises from glial cells (astrocytes, oligodendrocytes, ependymal cells). "Increased expression of each of NAT1, NAT2 and NAT10 correlated negatively with patient survival in the group of “all gliomas” patients." (PMID 26292663, 2015). "Another study on glioma showed that NAT10 could serve as a significant and effective prognostic factor in glioma." (PMID 39764566, 2025). "Additionally, our data demonstrated a positive correlation between NAT10 and PIK3R2 in glioma patients." (PMID 41408025, 2025).
laryngeal carcinoma (4 papers, 2020 to 2024). Carcinoma that arises from the laryngeal epithelium. "Previously, we discovered that MYCT1 suppresses laryngeal cancer cell migration through the CREB/MYCT1/NAT10 axis." (PMID 33680912, 2020). "NAT10‐mediated ac4C acetylation of FOXM1 promotes progression of laryngeal cancer." (PMID 39640362, 2024). "In addition, laryngeal cancer cell migration was reported to be promoted by the MYCT1/NAT10 axis." (PMID 34362389, 2021).
Myocardial fibrosis (4 papers, 2024 to 2025). "This regulatory axis (tsr007330/NAT10/EGR3) reveals a new mechanism for tsRNA regulation in myocardial fibrosis after MI, providing a new direction for targeted intervention." (PMID 40918194, 2025). "This study represents a pioneering investigation into the crucial function of NAT10‐mediated mRNA acetylation in the modulation of myocardial fibrosis." (PMID 39482983, 2024). "This work reveals the crucial role of NAT10‐mRNA ac4C acetylation in MI‐evoked myocardial fibrosis and TGF‐β1‐stimulated CFs proliferation and myofibroblasts." (PMID 39482983, 2024). "tsRNAs (rno-tsr007330) modulates myocardial fibrosis via NAT10-mediated EGR3 mRNA acetylation." (PMID 40565315, 2025). "The tsRNA tsr007330 is significantly downregulated after MI, and by antagonizing N-acetyltransferase NAT10, it inhibits the ac4C modification of early growth response protein 3 (EGR3) mRNA mediated by NAT10, thereby reducing myocardial fibrosis and improving cardiac function." (PMID 40918194, 2025). "Our research directly observed that NAT10 regulates the proliferation of CFs and the differentiation into myofibroblasts through mediating BCL‐XL mRNA ac4C acetylation, ultimately affecting the pathophysiological process of myocardial fibrosis." (PMID 39482983, 2024).
Obesity (4 papers, 2024 to 2025). Accumulation of substantial excess body fat. "There are few reports on the relationship between NAT10 and adipogenesis, as well as obesity." (PMID 40123006, 2025). "However, the role of NAT10 in adipogenesis and its contribution to obesity remains unclear, leaving an unexplored area of research." (PMID 40123006, 2025). "For instance, in obesity models, NAT10 knockdown reduces ac4C modification on KLF9 mRNA, destabilizes its transcripts, and suppresses downstream CEBPA/B-PPARG pathway activity, thereby inhibiting adipogenesis and alleviating high-fat diet-induced obesity." (PMID 40588654, 2025). "There is currently no report on whether Remodelin can prevent obesity by inhibiting NAT10 mediated mRNA ac4C modification." (PMID 40123006, 2025). "However, to date, there is no report whether Remodelin can prevent obesity by targeting NAT10-mediated mRNA ac4C modification." (PMID 40123006, 2025).